FTO (FTO alpha-ketoglutarate dependent dioxygenase)
Diseases named in the same sentence as FTO in open-access papers (continued):
Sharing a sentence is not in itself a finding about the gene and the disease.
Obesity (continued). "Recent data from a study of 354 children identified an interaction between dietary SFA and the ratio of total PUFA to SFA and obesity associated with FTO rs9939609." (PMID 23306188, 2013). "FTO minor allele (A allele) increased the risk of obesity by 2.8 times (95% CI = 1.3–6.0, P < 0.05) in adult females." (PMID 24102053, 2013). "Many allelic variants of fat mass and obesity associated (FTO) gene have been linked with BMI and obesity." (PMID 24102053, 2013). "Fat mass and obesity associated gene (FTO) is strongly associated with body mass index and obesity in human genome wide association studies." (PMID 24345215, 2013). "We found evidence that the previously reported common polymorphisms rs9939609 and rs1421085 in FTO gene increase the risk of obesity in the Portuguese children." (PMID 23342142, 2013). "Although rs9939609 variant of FTO gene is consistently associated with obesity in worldwide populations, sex and age dependence of such association in Pakistani population is a question worth consideration in future studies." (PMID 24102053, 2013). "The data were further analyzed for gender differences; FTO variant associated significantly with obesity (P < 0.01, 95% CI = 1.6–9.2) only in adult females (>18 years old)." (PMID 24102053, 2013). "Our study reported significant association of FTO variant with BMI and obesity in Pakistani females <45 years of age." (PMID 24102053, 2013). "In particular, common variants within the fat-mass and obesity associated (FTO) and melanocoritin 4 receptor (MC4R) genes are associated with modest effects on BMI (0.2–0.4 kg/m2 per allele) which translate into increased odds of obesity of 1.1–1.3 in adults." (PMID 23349760, 2013). "Genetic predisposition to obesity and FTO common variants contributed to increased insulin resistance among Europeans, but weakly increased type-2 diabetes risk, which is mediated by BMI itself." (PMID 23849767, 2013). "The fat mass and obesity associated gene (FTO) is widely investigated in humans regarding its important roles in obesity and type 2 diabetes." (PMID 24345215, 2013). "When the BMI effect was statistically accounted for the association disappeared, indicating that the diabetes risk associated with the FTO locus is mediated by obesity." (PMID 23997649, 2013). "Genetic variants in intron 1 of the fat mass– and obesity-associated (FTO) gene have been consistently associated with body mass index (BMI) in Europeans." (PMID 23341774, 2013). "Genetic variants within the fat mass– and obesity-associated (FTO) gene are associated with increased risk of obesity." (PMID 23341774, 2013). "The fat mass and obesity-associated (FTO) gene that has been associated with obesity in humans is also co-localized with oxytocin in both the PVN and SON." (PMID 23518828, 2013). "In the present study, where we studied 52 FTO variants spanning the whole gene, we validate the positive association of rs9939609 with obesity in Spanish children." (PMID 24289790, 2013). "In 2007, a strong association was detected between common single nucleotide polymorphisms (SNPs) in the first intron of the fat mass and obesity-associated gene (FTO), on the chromosome 16q12.2, and risk of obesity." (PMID 23342142, 2013). "This study explores the biological role of the Fat Mass and Obesity associated (FTO) gene locus on milk composition in German Holstein cattle." (PMID 23691044, 2013). "Limited cross-sectional analysis of the influence of dietary factors on BMI according to FTO rs9939609 genotype indicates that high-fat diets increase obesity risk." (PMID 23306188, 2013). "Further studies on other polymorphisms from FTO and other genes are needed, to establish the genetic basis contributing to the risk of obesity in the Portuguese population." (PMID 23342142, 2013).
Obesity (continued). "In a search of the literature for obesity-related genetic variants, we found that FTO rs9939609 was the most widely studied single nucleotide polymorphism (SNP), and has been found to exert strong effects on BMI, as well as diabetes." (PMID 23835106, 2013). "FTO has been wildly identified to be associated with body mass index (BMI) and obesity by large scale genome-wide association studies and a wealth of replication studies in several ethnicities, including Chinese." (PMID 23840863, 2013). "For this reason, we assessed the association of 52 SNPs spanning the FTO gene, with obesity in Spanish children; we also estimated the influence of these SNPs in anthropometric, clinical and metabolic parameters as well as inflammatory and CVD risk markers." (PMID 24289790, 2013). "Our results are consistent with previous studies demonstrating that SNPs in the first intron of FTO bear the strongest association with obesity, of the known BMI-raising SNPs, and also are strongly associated with extremes of obesity." (PMID 23950990, 2013). "The second gene, FTO, the fat mass and obesity associated gene, has been previously associated with BMI, obesity and type 2 diabetes in GWAS, and was recently associated with HDL-C in a large, gene-centric analysis of the CVD array used herein." (PMID 24116192, 2013). "FTO was the first susceptibility gene for obesity to be identified and together with BMI was reported to be associated with T2DM in European Caucasian subjects." (PMID 23431394, 2013). "Global deletion of this nuclear protein in mice leads to profound weight loss whereas a number of genetic variants in FTO predisposes individuals to the development of obesity." (PMID 24019958, 2013). "Association of FTO variant with BMI and obesity has been reported in East Asians and with T2D in Indians." (PMID 24102053, 2013). "Genome-wide association studies (GWAS) have repeatedly shown that the Fat Mass and Obesity associated (FTO) gene region is associated with differences in human body mass index (BMI), predisposition to type II diabetes and obesity." (PMID 23691044, 2013). "The association of FTO rs9939609 with class III obesity has been previously observed in the Mexican and several other populations." (PMID 23950976, 2013). "Given the mounting evidence showing a positive association between obesity and pancreatic cancer, this study aimed to investigate the relation between variants in the FTO gene, obesity and pancreatic cancer risk." (PMID 23835106, 2013). "FTO (fat mass and obesity-associated) gene was first identified in mouse and it has been associated with energy balance." (PMID 23849767, 2013). "It is widely recognized that, FTO, which increases the risk for obesity, is also a susceptibility gene for T2DM." (PMID 23431394, 2013). "With regard to GWAS in humans, the FTO region has been repeatedly associated with body mass index and obesity." (PMID 23691044, 2013). "Recently, a genome-wide association study has identified the fat mass- and obesity- associated gene (FTO) associated with higher body mass index (BMI) and risk of obesity in the Europeans." (PMID 23977173, 2013). "Numerous studies confirmed the association of FTO (fat mass and obesity associated gene) common variant, rs9939609, with obesity in European populations." (PMID 24102053, 2013). "Eight variants representing 8 early-life obesity-susceptibility loci, including FTO and MC4R, were genotyped in 2215 boys and 2449 girls aged 16 years from the population-based Northern Finland Birth Cohort 1986." (PMID 24040077, 2013). "Genome-wide association studies have shown that variance in the fat mass- and obesity- associated gene (FTO) is associated with risk of obesity in Europeans and Asians." (PMID 23977173, 2013). "First described in 2007, genetic variation in FTO has since become one of the most solidly confirmed risk factor for polygenic obesity in humans; yet, information about how FTO affects metabolism is still scarce." (PMID 23300491, 2013).
Obesity (continued). "Few studies have been carried out in population regarding the association of FTO gene variant, rs9939609, with obesity in South Asia." (PMID 24102053, 2013). "A recent Genome Wide Association study (GWAs) for type 2 diabetes mellitus (T2DM) susceptibility genes identified common variants in the FTO gene (fat mass and obesity associated) that predispose adults to diabetes through an effect on BMI." (PMID 23497514, 2013). "In summary, our study in dairy cattle provides evidence that the obesity-associated FTO gene region accounts for variation in milk fat yield." (PMID 23691044, 2013). "We examined the association of rs9939609 variant of FTO gene with obesity and obesity-related anthropometric and metabolic parameters in Pakistani population." (PMID 24102053, 2013). "Polymorphism of FTO gene contributes to the variation in plasma level of C-reactive protein, a marker of obesity-associated inflammation." (PMID 24345215, 2013). "We found strong associations with severe obesity for SNP rs9939609 within the FTO gene (P = 9.3×10−8) and SNP rs2815752 near the NEGR1 gene (P = 3.6×10−4), and directionally consistent nominal associations (P<0.05) for 12 other SNPs." (PMID 23950990, 2013). "This study aims to assess the association of three FTO polymorphisms (rs1861868, rs1421085 and rs9939609) with obesity-related outcomes in a sample of Portuguese children." (PMID 23342142, 2013). "The finding that the Fat Mass and Obesity (FTO) gene has been positively associated with BMI in COPD patients, suggests a potential genetic origin since this gene has been associated with differential fat deposition in the visceral o subcutaneos stores." (PMID 23762399, 2013). "As FTO has been identified to be susceptibility gene to obesity, the entanglement of obesity and PCOS suggests that adjustment analysis by BMI would not be as effective." (PMID 23840863, 2013). "Recently, the growth in studies regarding the association of obesity, or obesity-related traits, with SNPs in the FTO gene has been reported for several populations across the world." (PMID 23342142, 2013). "Our goal was to analyze the association of the fat mass and obesity- associated (FTO) gene rs9939609 variant (T/A) with the anthropometric and dietary intake phenotypes related to obesity in Brazilian children." (PMID 23497514, 2013). "Although variations in the FTO gene have been shown to be associated with increased cardiovascular risk, this is thought to be reflective of the prevalence of obesity in these individuals." (PMID 24019958, 2013). "The association of FTO rs9939609 variant with obesity has been replicated in different European populations and strongly pointed the association of this variant with diabetes." (PMID 24102053, 2013). "The association of FTO gene variants with body mass index (BMI) and other obesity characteristics is well established." (PMID 22817777, 2012). "Studies on obesity-associated genes in humans have identified several single nucleotide polymorphisms (SNP) in FTO intron 1 that are associated with obesity." (PMID 22510482, 2012). "A recent meta-analysis study, which included 18 studies, examined the effect of genetic variants in fat mass and obesity related gene (FTO gene) on MS." (PMID 22590636, 2012). "There was, on the other hand, a positive correlation between type 2 diabetes risk and higher BMI for 2 obesity (or insulin resistance)-associated loci–FTO and MC4R–as previously reported." (PMID 23173044, 2012). "We confirmed the association between the FTO rs9939609 and body mass and overweight/obesity risk in European children." (PMID 23155422, 2012). "In summary, we confirmed associations between the FTO rs9939609 and higher body mass and overweight/obesity risk in European children." (PMID 23155422, 2012). "At present energy intake is the only obesity-associated trait significantly and repeatedly associated with FTO variants in humans." (PMID 22675562, 2012).
Obesity (continued). "One most interesting gene from this region is FTO (fat mass and obesity associated), encoding 2-oxoglutarate-dependent nucleic acid demethylase." (PMID 22697793, 2012). "We found common genes including FTO, the fat mass and obesity associated gene, identified from significant SNPs by association studies of each trait." (PMID 23253381, 2012). "Genome-wide association studies have identified the FTO gene as the first susceptibility locus for common obesity." (PMID 23284729, 2012). "Three independent genome-wide (GWAS) studies reported significant association between obesity (determined by BMI) and common genetic variants in the fat mass and obesity-associated (FTO) gene including the SNP rs9939609." (PMID 23134754, 2012). "The effect of FTO variants on obesity parameters are shown to be generally smaller in Asian adults compared to European adults." (PMID 23091647, 2012). "In 2007, the fat mass and obesity associated (FTO) gene was identified as the first gene for common obesity by the genome-wide association study (GWAS)." (PMID 23049848, 2012). "In another recent meta-analysis, the level of physical activity was shown to modify the relationship between the FTO risk variant and body weight and risk of obesity." (PMID 23284729, 2012). "Among them, the role of the Fat Mass and Obesity Associated gene (FTO) has robustly and consistently been found to associate with common obesity." (PMID 23155422, 2012). "To date, of all identified loci, the genetic variation in FTO has the largest effect on obesity susceptibility." (PMID 22474595, 2012). "Next, we performed exploratory analysis to investigate association of FTO variants with biochemical markers of glucose metabolism, lipid metabolism, thyroid function and inflammation as all the parameters are related to obesity." (PMID 23091647, 2012). "Here we examined two variants rs9939609 and rs8050136 from first intron of FTO, which are most robustly implicated in obesity, for associations with obesity and related traits in 3,126 Indian children." (PMID 23091647, 2012). "In recent years, of the many genes studied for obesity, the FTO (fat mass- and obesity-associated) gene has been proven consistently to be associated with increased body mass index (BMI)." (PMID 22454631, 2012). "Independent studies have shown that several single nucleotide polymorphisms (SNP) in the human FTO (fat mass and obesity associated) gene are associated with obesity." (PMID 22510482, 2012). "Recent studies showed that polymorphisms in the Fat and Obesity-Associated (FTO) gene have robust effects on obesity, obesity-related traits and endophenotypes associated with Alzheimer's disease (AD)." (PMID 23251365, 2012). "The study provides first report of association of FTO variants with obesity and related anthropometric traits in Indian children with higher impact in children compared to adults." (PMID 23091647, 2012). "FTO variants are robustly associated with obesity and related traits in many population and shown to have variable impact during life course." (PMID 23091647, 2012). "Genetic factors play a major role in obesity, and genomewide association studies have provided evidence that several common variants within the fat mass- and obesity-associated (FTO) gene are significantly associated with obesity." (PMID 22454631, 2012). "We demonstrate here, for the first time, association of FTO variants with obesity risk and adiposity measures (BMI, weight, WC and HC) in Indian children." (PMID 23091647, 2012). "Numerous GWAS and subsequent replication studies in distinct population of European, African and Asian origin have robustly established association of FTO with obesity parameters, both in adults and children." (PMID 23091647, 2012). "Outside of the SHBG region we saw several SNPs with suggestive evidence of association, one of which (rs12596210) is intronic within the fat mass and obesity associated (FTO, Gene ID: 79068) gene." (PMID 22675492, 2012).
Obesity (continued). "This meta-analysis confirmed that the minor allele of the FTO rs9939609 variant increases the risk of obesity in adults and showed that this risk was reduced among physically active individuals by 27 %." (PMID 24392269, 2012). "Recently, a common variant in the FTO (fat, mass, and obesity) gene has been identified that predisposes to diabetes through an effect on the BMI." (PMID 23193389, 2012). "FTO rs9939609 was associated with higher body mass index (BMI), waist circumference (WC) and obesity (P<0.05 for all)." (PMID 23284998, 2012). "Among all the GWAS-identified obesity associated loci, FTO variants have strongest influence on obesity and contribute maximally to the variance in body mass index (BMI) in Europeans (0.34%) and East Asians (0.18%)." (PMID 23091647, 2012). "Recent studies suggest that FTO variants strongly correlate with obesity and mainly influence energy intake with little effect on the basal metabolic rate." (PMID 22675562, 2012). "Homozygous subjects with the variant FTO allele conclusively demonstrated a 20% higher risk for obesity (model adjusted for sex, age, center, diabetes, total energy intake, and physical activity; OR 1.20, 95% CI 1.04–1.38)." (PMID 23284998, 2012). "In conclusion, the data obtained in this study confirm a significant association of FTO polymorphisms with BMI and other anthropometrical characteristics of obesity variation in a middle-aged and elderly community-based sample of British women." (PMID 22817777, 2012). "Since its discovery, association of FTO locus has been demonstrated in adults and children from different ethnicities, not only with BMI but also with the risk of obesity, body fat percentage, waist circumference (WC) and other related traits." (PMID 23091647, 2012). "The strongest signal remains the association with variants within FTO (the fat-mass and obesity-related gene) (described in more detail below)." (PMID 22474595, 2012). "The present study would enable us to understand influence of FTO variants during early life in Indian population that are at higher risk to develop obesity in adult life." (PMID 23091647, 2012). "The human genetic association studies of FTO with obesity are further supported by subsequent functional studies in animal models." (PMID 23091647, 2012). "Here we examined association of FTO variants (rs9939609 and rs8050136) with obesity and related anthropometric and biochemical traits in 3,126 Indian children (aged 11–17 years) including 2,230 normal-weight and 896 over-weight/obese children." (PMID 23091647, 2012). "The FTO polymorphism was significantly associated with a higher prevalence of obesity (a 10% per-allele increase in the odds of being obese; 95%CI: 2%–17%)." (PMID 23284998, 2012). "The association between the common rs9939609 polymorphism of FTO with body mass index (BMI), other indices of adiposity and obesity risk has been consistently replicated in adult populations." (PMID 23155422, 2012). "The present study evaluated the effect of FTO variants (rs9939609 and rs8050136) on susceptibility to obesity and related traits in Indian children." (PMID 23091647, 2012). "The magnitude of the association and the risk for overweight/obesity conferred by FTO rs9939609 was comparable with that previously reported in other association studies in children, thus confirming this as a childhood obesity susceptibility gene." (PMID 23155422, 2012). "Nevertheless, the present study has replicated well the widely reported associations in young cohorts between FTO variants and anthropometrical indices of obesity, but in an older community-based sample of British women (aged 40 to 80, mean 52.8)." (PMID 22817777, 2012). "For example, mice deficient for the fat mass and obesity associated (FTO) gene (FTO−/−) have been reported to have phenotypic differences when compared to mice that were homozygous for the ENU hypomorphic mutant FTOI367F." (PMID 22912827, 2012).